IL16 (interleukin 16)
Diseases named in the same sentence as IL16 in open-access papers (continued):
Sharing a sentence is not in itself a finding about the gene and the disease.
gout (2 papers, 2023 to 2025). A condition characterized by painful swelling of the joints, which is caused by deposition of urate crystals. "In a previous study, cytokines such as interleukin (IL)-16 and IL-18, which are common mediators of inflammation, exhibited strong associations with the severity of gout." (PMID 40364122, 2025). "We observed that the CCL and IL-16 signaling pathways among monocyte subtypes were greatly increased in gout flares." (PMID 38063198, 2023). "By comparing the information flow between gout flares and remission, we identified that 15 of 42 pathways were highly active during gout flares, including 9 pathways involved in inflammatory and immune responses, such as CCL, IL-16, MHC-II, CLEC, GLAECTIN, ITGB2, and ALCAM." (PMID 38063198, 2023).
hyperreactivity (2 papers, 2017 to 2022). "Caspase-3 plays an important role in changing pro-IL-16 to the mature cytokine and IL-16 affects allergen-induced airway hyperreactivity and the up-regulation of IgE." (PMID 29160801, 2017).
idiopathic pulmonary fibrosis (2 papers, 2020 to 2022). Idiopathic pulmonary fibrosis (IPF) is a nonneoplastic pulmonary disease that is characterized by the formation of scar tissue within the lungs in the absence of any known cause. "Furthermore, there was a study showing that pro-fibrotic mediators induce IL-16 upregulation and IL-16 gene expression was elevated in lung tissue from patient with idiopathic pulmonary fibrosis." (PMID 32264927, 2020).
insomnia (2 papers, 2024 to 2026). A sleep disorder characterized by difficulty in falling asleep and/or remaining asleep. "Up to 54.1% of the variance in the insomnia score was predicted by IL-16 and SCGF (both positively) and sIL-1RA (inversely)." (PMID 38538641, 2024). "Nominal significance (P < 0.05) was observed for negative correlations with panic disorder, insomnia, interleukin-16, multisite chronic pain, and heart rate, whereas a positive correlation was noted for the religious group." (PMID 41152404, 2026).
ischemia (2 papers, 2020 to 2025). A hypoperfusion of the BLOOD through an organ or tissue caused by a PATHOLOGIC CONSTRICTION or obstruction of its BLOOD VESSELS, or an absence of BLOOD CIRCULATION. "The concentrations of Il‐6, Tnfα, Il‐16, Fcgr3α, and Nos2 were elevated following ischemia/reperfusion, which were partially mitigated by RF." (PMID 39915908, 2025).
malaria (2 papers, 2018 to 2023). Malaria is a serious and sometimes fatal disease caused by a parasite that commonly infects a certain type of mosquito which feeds on humans. "Further, our EigenGWAS analysis did not detect signatures of divergent selection between archipelagos in the regions surrounding the malaria candidates RIMS4 or IL‐16." (PMID 30283662, 2018).
MRSA pneumonia (2 papers, 2021 to 2025). "In MRSA infected mouse lungs infiltrating immune cells express IL-16 and neutralizing anti-IL-16 Ab improved clearance of MRSA pneumonia in mice." (PMID 40529362, 2025).
Myocardial fibrosis (2 papers, 2013 to 2025). "Modern studies have shown that IL-16 plays a central role in promoting myocardial fibrosis by prompting the release of TGF-β1 from macrophages infiltrated with cardiomyocytes." (PMID 40881586, 2025). "Our results suggested that IL-16, a cytokine which has been shown to be a key mediator of several inflammatory, allergic, or infectious diseases, promotes myocardial fibrosis, leading to increased LV myocardial stiffness." (PMID 23894370, 2013). "Our data indicate that IL-16 is a mediator of LV myocardial fibrosis and stiffening in HFpEF, and that the blockade of IL-16 could be a possible therapeutic option for HFpEF." (PMID 23894370, 2013). "Interleukin-16 (IL-16) is mainly secreted by T-lymphocytes, epithelial cells, fibroblasts, and monocytes, and has been shown to be a key mediator of several inflammatory, allergic or infectious diseases, as well as playing an important role in promoting myocardial fibrosis." (PMID 40881586, 2025).
nasal polyps (2 papers, 2016 to 2024). "At the cytokine level, earlier studies investigated specific cytokines and their mechanisms in polypogenesis, reporting increased IL-6 and IL-8 levels in nasal polyps, and serum IL-16 levels were found to be elevated in patients with nasal polyposis." (PMID 38790942, 2024).
Neonatal sepsis (2 papers, 2022 to 2025). Systemic inflammatory response to infection in newborn babies. "MiR-1184 downregulation serves as a diagnostic biomarker for neonatal sepsis, regulating LPS induced inflammatory response by inhibiting IL-16 in monocytes." (PMID 40661956, 2025).
pancreatitis (2 papers, 2017 to 2019). Inflammation of the pancreas. "The association of SNPs in MYBBP1A, SPEF2 and IL16 geneswith pancreatitis was replicated in the validation cohort (p ≤0.05) as well as in combined cohort (p=0.0003, p=0.008 and p=0.02, respectively)." (PMID 28574850, 2017). "The only noteworthy observation was related to the association of IL16 with pancreatitis." (PMID 28574850, 2017). "Accordingly, G allele carriers of the rs11556218 SNP in the IL16 gene and carriers of the A allele in the rs34708521 SNP of the SPEF2 gene, were at higher risk of pancreatitis in both discovery and replication cohorts." (PMID 28574850, 2017). "Furthermore, the analysis in the context of a larger sample size provided by the combined cohort further supports the correlation between the SNPs in MYBBP1A, IL16 and SPEF2 with pancreatitis as the associations gained more significance in the pooled sample." (PMID 28574850, 2017).
psychosis (2 papers, 2022 to 2023). "The main inflammatory factors associated with clinical outcome in psychosis were IL-15, IL-13, IL-16, and IL-8, which may be associated with poor clinical outcome." (PMID 37270510, 2023). "The main inflammatory markers associated with clinical outcome in psychosis were IL-15, IL-13, IL-16, and IL-8, which may be associated with poor clinical outcome." (PMID 35273531, 2022).
Sézary syndrome (2 papers, 2016 to 2023). "IL16 was also downregulated, reflecting the pattern observed in severe Sézary syndrome." (PMID 38026637, 2023). "In addition, the authors suggested IL-16 as a marker of AD, SLE and Sezary's syndrome activity." (PMID 27788245, 2016).
vitiligo (2 papers, 2021 to 2025). Generalized well circumscribed patches of leukoderma that are generally distributed over symmetric body locations and is due to autoimmune destruction of melanocytes. "Therefore, NR-046211.1 may regulate the pathogenesis of vitiligo through NR-046211.1/mir-328/IL1β axis, but NR-046211.1/mir-637/IL16, and NR-046211.1/mir-637/IL34 axis need further confirmation." (PMID 34941177, 2021). "Therefore, ENST0000460164.1 may act through the ENST0000460164.1/mir-637/IL16 or ENST0000460164.1/mir-637/IL34 axis in vitiligo." (PMID 34941177, 2021).
Whipple disease (2 papers, 2007 to 2010). A systemic infection caused by the Gram-positive bacterium Tropheryma whipplei. "The replication of Tropheryma whipplei (the agent of Whipple's disease) within human macrophages is associated with the expression of IL-16, a cytokine known for its chemotactic and inflammatory properties." (PMID 21042409, 2010). "Whipple's disease (WD) is an infectious disease caused by Tropheryma whipplei, which replicates in macrophages and induces the release of interleukin (IL)-16, a substrate of caspase 3, and macrophage apoptosis." (PMID 17551575, 2007).
acute liver failure (1 paper, 2019). Rapid deterioration of liver function causing encephalopathy and coagulopathy. "CCL11 (Eotaxin) was selectively increased in biliary atresia patients, while IL-3, IL-6, CXCL8 (IL-8), IL-9, IL-16, MIF, CCL4 (MIP-1 β), and CXCL1 (GRO-α), were increased in both biliary atresia and acute liver failure." (PMID 30740106, 2019).
AIDS (1 paper, 2007). A syndrome resulting from the acquired deficiency of cellular immunity caused by the human immunodeficiency virus (HIV). "Interestingly, T cell clones from LTNP individuals express higher levels of IL-16 than cells from AIDS patients." (PMID 17651505, 2007).
allergic asthma (1 paper, 2012). A asthma with a basis in a pathological type I hypersensitivity reaction. "Epithelial and subepithelial IL-16 immunoreactivity has been associated with increased bronchial responsiveness in humans with allergic asthma and in an animal model of allergic asthma." (PMID 22563393, 2012).
allergic conjunctivitis (1 paper, 2023). "In 2020, Shoji demonstrated that tear levels of CCL17/TARC, CCL24/eotaxin-2, and IL-16 in VKC and AKC patients were significantly higher than in patients with other allergic conjunctivitis, like SAC and PAC (p < 0.01)." (PMID 37658939, 2023).
Anxiety (1 paper, 2024). Intense feelings of nervousness, tension, or panic often arise in response to interpersonal stresses. "Regression #2 shows that 45.4% of the variance in the pure_anxiety score was explained by IL-16 and IL-17 (both positively) and CCL3 (inversely)." (PMID 38538641, 2024).
arteriosclerosis (1 paper, 2025). A vascular disorder characterized by thickening and hardening of the walls of the arteries. "Studies have demonstrated that inflammatory mediators such as fractalkine/CX3CL1, CCL8, M-CSF, HGF, E-selectin, PI3/elafin, CCL17, and IL-16 are significantly elevated in patients with AD, contributing to the progression of arteriosclerosis." (PMID 40757030, 2025).
atopic asthma (1 paper, 2024). An asthma that is characterized by symptoms that are triggered by an allergic reaction caused by inhaled allergens such as dust mite allergen, pet dander, pollen and mold. "The secondary analysis using the eQTL cytokines in lung tissue produced qualitatively similar results to the main eQTL analysis, but associations were nominally significant only for IL-18 in relation to FEV1, FVC, and COPD, and IL-16 in relation to atopic asthma." (PMID 39319267, 2024).
autism (1 paper, 2023). Persistent deficits in social interaction and communication and interaction as well as a markedly restricted repertoire of activity and interest as well as repetitive patterns of behavior. "Besides, elevated IL-16 expression was already associated with the development of immune dysfunction in children with autism, and IL-16-expressing CD4+ and CD8+ T lymphocyte numbers were higher in children with ASD compared to typically developing controls." (PMID 37305482, 2023).
biliary atresia (1 paper, 2019). A rare, biliary tract disease characterized by progressive obliterative cholangiopathy of the intra- and extrahepatic bile ducts, occurring in the embryonic/ perinatal period, leading to severe and persistent neonatal jaundice and acholic stool. "In children with biliary atresia, serum levels of CCL11 (Eotaxin), IL-16, and GRO-α (CXCL1), as well as numbers of B lymphocytes, were higher than in children with ALF or liver tumors." (PMID 30740106, 2019).
brain cancer (1 paper, 2018). A primary or metastatic malignant neoplasm affecting the brain. "In this nested case-control study of first primary brain cancer among active component military personal with serially collected pre-diagnostic serum samples, we found inverse, independent associations between levels of IL-15 and IL-16 and risk of cancer." (PMID 30297770, 2018). "Of 14 cytokines examined, significant inverse associations with brain cancer risk were found for IL-15 and IL-16 when these were modelled either as a quartile trend (P = 0.002 and P = 0.001, respectively) or a log-linear trend (P = 0.001 and P = 0.004, respectively)." (PMID 30297770, 2018). "Our study provides new evidence concerning the possible importance of IL-15 and IL-16 in the aetiology of brain cancer with young and middle age onset." (PMID 30297770, 2018).
brain glioma (1 paper, 2018). A malignant glioma that involves the brain. "In conclusion, novel associations with pre-diagnostic serum levels of IL-15 and IL-16 and their modification by history of diagnosis of immune-related conditions support the importance of immune alterations in the aetiology of young- and middle-age-at-onset brain glioma years before diagnosis." (PMID 30297770, 2018).
brain inflammation (1 paper, 2025). "The study found that in CSF1R mutant mice, the levels of inflammatory cytokines (such as IL-16 and IL-1β) were significantly elevated, indicating that microglial activation and pro-inflammatory responses exacerbate brain inflammation." (PMID 40893935, 2025).
brain tumours (1 paper, 2017). "The role of IL-16 in brain tumours has not been elucidated, although occasional reports have described IL-16 secretion by myeloid cells in astrocytic tumours." (PMID 28417956, 2017).
bullous pemphigoid (1 paper, 2025). Bullous pemphigoid (BP) is the most common form of autoimmune bullous dermatosis. "Our review identified keratinocytes as crucial mediators in bullous pemphigoid, predominantly orchestrating Th2-driven inflammation through secretion of cytokines including IL-16, leading to CD4+ T cells recruitment and amplification of the IL-4/IL-13 axis." (PMID 41479908, 2025).
Cachexia (1 paper, 2025). Severe weight loss, wasting of muscle, loss of appetite, and general debility related to a chronic disease. "IL‐16 could be an interesting therapeutic target in modulating inflammation and metabolism in cachexia." (PMID 41267538, 2025).
cardioembolic stroke (1 paper, 2021). "Positive association of IL-1 with cardioembolic stroke and suggestive inverse associations of IL-6 with any IS, cardioembolic stroke, and small vessel stroke, and of IL-16 with CAD." (PMID 34456968, 2021).
Chlamydial infection (1 paper, 2014). "Compared to group (i), we observed increased secretion of five cytokines (MIF/GIF, Serpin E1, RANTES, IL-6, IL-8) and five chemokines (ENA-78, IL-16, IP-10, MIG, MIP-1α/β) following wIRA/VIS-exposure, chlamydial infection or both." (PMID 25019934, 2014). "Chlamydial infection, irradiation, and the combination of both showed a similar release pattern of a subset of pro-inflammatory cytokines (MIF/GIF, Serpin E1, RANTES, IL-6, IL-8) and chemokines (IL-16, IP-10, ENA-78, MIG, MIP-1α/β) from host cells." (PMID 25019934, 2014).
Chronic colitis (1 paper, 2023). A chronic inflammatory disease of the large intestine (colon, cecum and rectum). "Another species of Parabacteroides, Parabacteroides distasonis, also demonstrated anti-inflammatory properties by preventing an increase in pro-inflammatory cytokines such as IFNγ, IL-12, IL-17 and IL-16 in mice after induced acute or chronic colitis." (PMID 37504910, 2023).
chronic fatigue syndrome (1 paper, 2017). "In addition, analyses of serum from myalgic encephalomyelitis and chronic fatigue syndrome patients (conditions that are considered closer to GWI patients) have revealed decreased levels of IL-16 and IL-7." (PMID 28659758, 2017).
chronic hepatitis B infection (1 paper, 2014). "Our results are in concordance with previous studies and we suggest that Il-16 is related to hepatitis B infection and Il-16 gene polymorphisms are considerable host genetic factors for patients' susceptibility to chronic hepatitis B infection." (PMID 25692036, 2014). "Present study was designed to investigate the relationship between three SNPs of Il-16 gene and patients' susceptibility to chronic hepatitis B infection and to determine the effect of Il-16 gene polymorphisms on development of chronic HBV infection." (PMID 25692036, 2014). "According to the results of our study, rs11556218 T>G, rs4778889 T>C, and rs4072111 C>T polymorphisms of Il-16 gene are associated with patients' susceptibility to chronic hepatitis B infection." (PMID 25692036, 2014). "There is limited data about the association of SNPs in the Il-16 gene sequence and risk of chronic hepatitis B infection, whereas the role of cellular immunity in dealing with hepatitis HBV infection is clear and on the other hand CD4 (receptor of Il-16) is involved in this process." (PMID 25692036, 2014).
chronic mountain sickness (1 paper, 2021). A pathological condition resulting from chronic exposure to hypoxia at high altitude. "However, IL-16 has not been reported in chronic mountain sickness before." (PMID 34483727, 2021).
cystic fibrosis (1 paper, 2016). Autosomal recessive disorder caused by pathogenic variants in the CFTR gene (cystic fibrosis transmembrane conductance regulator), which encodes a chloride and bicarbonate channel expressed in epithelial cells, and follow the diagnosis criteria. "CuFi-8 cells are derived from a patient with cystic fibrosis, and IL-16 has been shown to be dysregulated in this disease." (PMID 26807786, 2016).
demyelinating disease (1 paper, 2015). A broad group of disorders that affect the myelin sheaths that cover the neurons. "Uncovering those IL-16-specific mechanisms is critical for the development of new CD4+ T cell subset-targeted therapies for MS and other chronic and/or progressive inflammatory and demyelinating diseases." (PMID 25896927, 2015).
dermatitis (1 paper, 2023). An inflammatory process affecting the skin. "All mice with oxazolone-induced dermatitis had a dramatic increase in IL-1β, IL-4, IL-6, IL-10, TNF-α, IFN-γ, IL-16, IL-17C, IL-17E, IL-17F, IL-21, IL-22, and MIP-3a, whereas the concentrations of IL-12p70, IL-2, IL-17A, and IL-23 were lower in dermatitis mice." (PMID 37889696, 2023).
dysentery (1 paper, 2022). Acute inflammation of the intestine associated with infectious diarrhea of various etiologies, generally acquired by eating contaminated food containing toxins, biological derived from bacteria or other microorganisms. "Increased levels of GM-CSF and reduced production of TNF-β, IL-1β, IL-17A, IL-16, IL-4, and IL-10 were distinct responses observed in Shigella-infected children with dysenteric diarrhea compared to Shigella without dysentery." (PMID 35924851, 2022). "The presence of IL-1β, IL-4, IL-16, and tumor necrosis factor beta (TNF-β) was associated with the absence of dysentery." (PMID 35924851, 2022). "Children with dysenteric Shigella had lower levels of IL-16, IL-4, and IL-10 in their stools than children with Shigella without dysentery after adjustment for age and sex (blue circles)." (PMID 35924851, 2022). "Comparison of the response ratios of cytokines that were significantly different between children with and without dysentery confirmed that dysenteric Shigella was associated with >4-fold-higher levels of GM-CSF and reduced production of TNF-β, IL-1β, IL-16, and IL-4." (PMID 35924851, 2022).
E. coli infection (1 paper, 2023). "Therefore, we also investigated the transcriptional changes in interleukin-family genes and found that E. coli infection significantly increased the expressions of IL-1α, IL-11, NFIL-3, IL-16, and other cytokines." (PMID 36876070, 2023).
eating disorder (1 paper, 2021). A broad group of psychological disorders with abnormal eating behaviors leading to physiological effects from overeating or insufficient food intake. "In the full sample, associations between BMI and some inflammatory markers (e.g., GM-CSF, IL-8, IL-6, IL-16, IP-10) were mirrored by an inverse relationship with eating disorder psychopathology." (PMID 34442458, 2021).
endocarditis (1 paper, 2007). Inflammation of the endocardium. "As compared to the infective endocarditis due to C. burnetii, untreated patients with endocarditis due to T. whipplei exhibited significantly (p<0.01) higher levels of circulating IL-16 and nucleosomes." (PMID 17551575, 2007).
endotoxemia (1 paper, 2018). "However, future detailed analyses of CCL3, IL-16, and IL-1α in this setting might provide additional insights into potential mechanisms mediating the observed protection against endotoxemia." (PMID 29928698, 2018).